BRAF (B-Raf proto-oncogene, serine/threonine kinase)
Diseases named in the same sentence as BRAF in open-access papers (continued):
Sharing a sentence is not in itself a finding about the gene and the disease.
melanoma (continued). "Based on the results of these RCTs, niv/ipi is recommended as first‐line treatment for BRAF‐mutated melanoma." (PMID 38087810, 2024). "About 10 years ago, vemurafenib and dabrafenib were approved by the Food and Drug Administration for the treatment of advanced melanoma with BRAF mutation." (PMID 38541077, 2024). "Modern therapies targeting the BRAF gene mutation in advanced melanoma have significantly improved patient outcomes but pose cardiovascular risks." (PMID 39272803, 2024). "These inhibitors have shown efficacy both as monotherapy in patients with unresectable, metastatic melanoma and as adjuvant therapy in stage III melanoma patients with BRAF mutations." (PMID 38891988, 2024). "Melanomas of the skin are known to harbor BRAF p.V600E mutations, which can be detected on both IHC and molecular testing." (PMID 38509523, 2024). "In a study that reviewed the somatic mutation profiles of 467 melanoma patients, BRAF was identified as one of the most mutated genes within the patient cohort." (PMID 39336897, 2024). "Another crucial discovery in advanced melanoma has been the fact that approximately 45% of patients harbor a BRAF mutation within their tumor cells." (PMID 38610925, 2024). "Brain metastasis is a common and severe complication in melanoma patients with BRAF and NRAS mutations, often resulting in a poor prognosis." (PMID 39582535, 2024). "Among them, encorafenib plus binimetinib (enco/bini) combination therapy is one of the optimal chemotherapies for BRAF-mutated advanced melanoma." (PMID 39337055, 2024). "Mutations in the BRAF gene occur in ~40–85% of melanoma cases, with the lowest frequency in primary melanomas, increased in metastatic sites, and the highest in recurrent melanomas, while NRAS mutation occurs in ~25%." (PMID 39766280, 2024). "The UV causes damage to DNA structure, resulting in the development of melanoma, where the two most common BRAF gene mutations - V600E and V600K occur." (PMID 39764216, 2024). "The study also delved into the impact of melanoma subtype and BRAF mutation status on the effectiveness of adjuvant therapy, emphasizing the need for further investigation." (PMID 38212945, 2024). "In the largest cohort of patients with melanoma, BRAF mutations were identified in 67% of patients with leptomeningeal carcinomatosis versus 47% in the general population of patients with melanoma." (PMID 38921299, 2024). "Analysis of blood samples from advanced BRAF-mutated melanoma patients revealed a decrease in CTC numbers with treatment, accompanied by a positive correlation between CTC numbers and tumor regression." (PMID 38398206, 2024). "One of the most extensively studied mutations is the BRAF mutation, which is present in notable proportion of melanoma cases." (PMID 39025927, 2024). "In approximately 44% of melanomas, BRAF mutations are accompanied by PTEN loss, an outcome that promotes high levels of immunosuppressive elements such as myeloid-derived suppressor cells and low levels of natural killer (NK) and cytotoxic T cells." (PMID 39336897, 2024). "In this study, we evaluated the IdyllaTM system for BRAF mutation testing in comparison to NGS in 51 melanoma patients, comparing concordance rates, turnaround times, and impact on treatment decisions." (PMID 39125519, 2024). "The proposed inhibitor combination was chosen because it is clinically used in the treatment of melanoma patients with a BRAF mutation." (PMID 39175042, 2024). "In the COMBI-AD phase III trial, 870 patients with completely resected, stage III BRAF-mutated melanoma were randomized to receive oral dabrafenib plus trametinib or placebo for 12 mo after surgery." (PMID 39542696, 2024). "Real-world data indicates that sarcoidosis caused by immune checkpoints or BRAF/MEK inhibitors occurs more frequently than reported in Phase 3 melanoma clinical trials." (PMID 39717410, 2024).
melanoma (continued). "The most common BRAF mutation seen in melanoma is V600E which is present in about 80–90% of all BRAF mutated cases, with V600K accounting for another 15% and the less common V600D/G/R/M occurring in less than 5% of cases." (PMID 39207855, 2024). "In this study, we identified that collagen triple helix repeat containing 1 (CTHRC1) expression was associated with the BRAF(V600E) mutation in colon cancer, thyroid cancer, and melanoma." (PMID 39052013, 2024). "In Western populations, patients with melanoma are predominantly affected by the cutaneous type, with BRAF gene mutations accounting for 50%–60%, of which over 90% are class I V600 mutations." (PMID 39529955, 2024). "BRAF mutation was independently associated with improved recurrent-free survival (RFS) in patients with stage three melanoma who were treated with adjuvant pembrolizumab." (PMID 38611025, 2024). "Other approaches include BRAF inhibitors such as Dabrafenib, Encorafenib, or Vemurafenib in melanoma with mutated or activated BRAF genes or MEK inhibitors or combinations thereof." (PMID 39682251, 2024). "Therapeutic agents designed to target cancers harboring BRAF mutations represented a pioneering class of targeted therapies for the treatment of advanced melanoma." (PMID 39610923, 2024). "To address this, we conducted in vitro cytotoxicity assays using melanoma cell lines harboring either BRAF wild-type (WT) (SK-MEL-2) or BRAFV600E mutations (SK-MEL-28 and A375)." (PMID 39061208, 2024). "Despite harboring the BRAF mutation as the common denominator of the tested melanoma cell lines, melanoma cells displayed varying inter-tumoral heterogeneity affecting treatment response and potential resistance." (PMID 38730718, 2024). "BRAF (V600E) mut has been implicated in melanoma progression, senescence evasion, apoptosis, uncontrolled replication potential, and angiogenesis, resulting in tissue invasion and metastasis." (PMID 39099686, 2024). "According to previous literature, ∼50% of melanomas harbor mutations in the BRAF gene, of which the vast majority encodes the BRAF-V600E oncoprotein." (PMID 38839106, 2024). "Although 63–76% of patients with advanced melanoma and BRAF V600E mutations benefited clinically from combination therapy, the median progression-free survival was only approximately 9 months, and 90% of patients experienced resistance within one year." (PMID 38462618, 2024). "Individuals with uncommon BRAF mutations can exhibit a response to targeted treatment, although the effectiveness appears to be less pronounced when compared to V600E mutated melanoma." (PMID 39582535, 2024). "Approximately 66% of melanomas have a BRAF gene mutation, predominantly a BRAF V600E-activating mutation, which accounts for up to 92% of BRAF mutations in melanoma." (PMID 39200941, 2024). "In the context of treating BRAFV600E mutation-positive melanoma, vemurafenib and dabrafenib have shown significant efficacy, leading to significant improvements in PFS and OS for patients with BRAF-mutated melanoma." (PMID 38474231, 2024). "Vemurafenib is approved for the treatment of malignant melanoma with mutations detected using the Cobas BRAF V600 Mutation Detection Kit in Japan." (PMID 38167464, 2024). "The most frequently seen primary oncogenic event in melanomas is the BRAF-activating mutation, which leads to permanent activation of the MAPK pathway and subsequently promotes uncontrolled cell proliferation, survival, and other oncogenic processes." (PMID 38247727, 2024). "Common mutations in NRAS and BRAF observed in melanoma activate the RAS/RAF/MAPK and PI3K/AKT signaling pathways." (PMID 38504984, 2024). "A phase 3 trial (DREAMseq) in previously untreated BRAF‐mutated melanoma compared niv/ipi as first line and then switched to dab/tra at disease progression with dab/tra as first line and then switched to niv/ipi at disease progression." (PMID 38087810, 2024).
melanoma (continued). "RAC1 mutations are present in 2–9% melanomas, usually in association with activation mutations in BRAF or NRAS, or inactivating mutations in NF1." (PMID 40396280, 2024). "We observed highly increased p-ERK levels in response to a 20 h treatment with the eIF4A helicase inhibitor in both melanoma subtypes, despite the presence of strong oncogenic BRAF and NRAS mutations already highly activating the ERK pathway in these cells." (PMID 39436655, 2024). "Though the rate of BRAF mutations is low in mucosal melanomas, the rate of c-KIT mutation is often higher than is present in traditional cutaneous melanoma." (PMID 39001457, 2024). "Previous trials of targeted drug therapies that block an overactive growth pathway in melanoma cells containing a BRAF V600-mutation have demonstrated responses but with short durability." (PMID 38725995, 2024). "MAPK signaling is the main oncogenic driver in metastatic melanomas bearing activating mutations in the BRAF oncogene." (PMID 38472212, 2024). "BRAF mutated solid tumour cases other than BRAF V600E mutated colorectal cancer, melanoma, and non-small cell lung cancer cases were included." (PMID 38333370, 2024). "In this study, it was observed that the expression of the BRAF gene in A-375 melanoma cells, which is known to have the BRAF-V600E mutation that causes skin cancer, was significantly inhibited by UA treatment." (PMID 39473730, 2024). "The current therapeutic algorithm for stage IV melanoma comprises Targeted Therapy for patients positive to BRAF V600E mutations, followed by Immune-Checkpoint blockade as a preferential step via PD1 and/or CTLA4 inhibition and chemotherapy." (PMID 38184610, 2024). "Targeted therapy is a valid treatment option for older BRAF mutated melanoma patients, preferably after exposure to ICI when medically feasible." (PMID 39207855, 2024). "Despite their high efficacy, secondary resistance within a short time has been observed in most of the patients with BRAF-mutated melanomas." (PMID 38183141, 2024). "More than 90% of all clinically recorded BRAF-mutated melanomas carry a V600E mutation, which can be targeted pharmacologically by inhibition of BRAF itself or the downstream kinase MEK with drugs like dabrafenib and trametinib, respectively." (PMID 39165562, 2024). "The BRAF-V600E mutation makes up to 90% of all BRAF mutations, is expressed in 40–60% of all human melanoma patients, and is more common in younger patients." (PMID 38254853, 2024). "Dabrafenib (GSK2118436) has demonstrated significant efficacy as an anticancer drug, particularly benefiting patients with melanoma characterized by BRAF gene mutations." (PMID 39582535, 2024). "Somatic mutations to key genes such as BRAF are common risk factors associated with melanoma development in more than 5% of patients with BRAF mutation." (PMID 38275910, 2024). "BRAF is a serine-threonine-specific kinase whose most common mutation occurs at codon 600 in melanoma." (PMID 38732242, 2024). "Ipilimumab-nivolumab showed advantages for BRAF mutations, implying their relevance in selecting between single or combined checkpoint inhibition for advanced melanoma therapy." (PMID 39582535, 2024). "There is an association between the prevalence of BRAF gene mutations in melanoma patients with respect to different ethnic groups." (PMID 39195270, 2024). "Although the majority of melanomas are characterized by a clonal mutation in either BRAF or NRAS, likely limiting the added clinical value of mFast‐SeqS in patients with melanoma, we demonstrated that ddPCR showed a high correlation with mFast‐SeqS." (PMID 38790134, 2024).
melanoma (continued). "Early studies suggest that BRAF mutation is an early event in melanoma development, representing a distinct subtype of melanoma with unique characteristics and clinical outcomes." (PMID 38534309, 2024). "Histopathological examination confirmed superficial spreading malignant melanoma (pT3bN2aM0, Stage IIIc) with a BRAF V600E mutation." (PMID 39669853, 2024). "Trametinib has been approved by the FDA for the treatment of human melanoma with BRAF V600E or V600K mutations and has shown efficacy in inhibiting tumor growth and improving survival in patients with BRAF mutant melanoma." (PMID 39408717, 2024). "BRAF gene mutations occur in about 40%-50% of patients with advanced melanoma, leading to activation of the mitogen-activated protein kinase (MAPK) signaling pathway, increasing cellular expansion and replication." (PMID 39534873, 2024). "In summary, this work describes BRAF/MEK-inhibitor-resistant melanoma cells, allowing for better understanding the underlying mechanisms of resistance." (PMID 39175042, 2024). "Other canine tumors exhibiting the BRAF V595E mutation include pulmonary carcinoma, oral squamous cell carcinoma, melanoma, glioma, and peripheral nerve sheath tumor, but their mutation rates are less than 25%." (PMID 39272320, 2024). "Human melanomas are often driven by well-defined genetic mutations (e.g., BRAF, NRAS, and KIT mutations) that can be targeted by specific therapies." (PMID 39408717, 2024). "Bioinformatics analyses were used to identify the association of polyamine biosynthesis with BRAF inhibitor resistance and poor prognosis in melanoma patient cohorts." (PMID 38965534, 2024). "We and others have previously deployed ctDNA to detect actionable oncogenic events in solid tumors including melanoma and anaplastic thyroid carcinoma such as the V600E BRAF mutation." (PMID 38549938, 2024). "A study identified BRAF V600E and V600K mutations in circulating tumor cells from patients with melanoma, indicating potential benefit from BRAF inhibitors." (PMID 38398206, 2024). "This led to the approval of nivolumab plus ipilimumab combination therapy for BRAF wild‐type melanoma in the USA in September 2015, which was later extended to BRAF‐mutated melanoma." (PMID 38087810, 2024). "Such as BRAF or KRAS mutations in EGFR‐TKI‐treated lung cancer, or MEK mutations in BRAF inhibitor resistant malignant melanoma." (PMID 39184861, 2024). "The TRICOTEL trial examined a triple combination of targeted therapy with immunotherapy in BRAF V600 mutation-positive melanoma patients with CNS metastases." (PMID 39469641, 2024). "The evaluation of BRAF mutations in nevi and melanomas has shown statistically significant differences between the two types of samples in terms of patients’ prevalence." (PMID 38396984, 2024). "Further, advanced melanoma patients with the BRAF V6000K mutation have poorer survival when compared to those with the V600E mutation." (PMID 38730723, 2024). "Abnormal expression of BRAF gene has been found in multiple tumors, and its abnormal expression is associated with the pathogenesis of melanoma and thyroid cancer." (PMID 38178263, 2024). "The frequency of this mutation has sparked research investigating the effects of BRAF inhibition on melanoma." (PMID 39682188, 2024). "For these reasons, it makes sense to use the determination of ctDNA of the BRAF oncogene in peripheral blood to identify high‐risk patients with early stages of melanoma using the most sensitive methods, such as droplet digital PCR." (PMID 39387479, 2024). "Our research indicates a potential novel combination therapy (alantolactone and MAPKi) for patients with BRAF-mutated melanoma." (PMID 38822350, 2024). "Most melanomas are associated with mutational activation of the BRAF gene, and missense mutations of BRAF have been reported to be the oncogenic form in approximately 70% of melanomas, compared to a low frequency of mutations in other human cancers." (PMID 39408810, 2024).
melanoma (continued). "With this review, we set out to clarify the type, incidence and relative risk of adverse oral events in melanoma patients treated with the combination of BRAF and MEK inhibitors." (PMID 38201012, 2024). "Trametinib, as a monotherapy, first received its FDA approval for the treatment of some melanomas carrying certain BRAF mutations and was subsequently approved as a combinational therapy for some solid tumors including gliomas and NSCLC." (PMID 38259097, 2024). "For example, the V600E mutation in BRAF (melanoma) and the L858R mutation in EGFR (non-small cell lung cancer), are thought to destabilize the inactive αC-out conformation, creating a constitutively active kinase." (PMID 38778760, 2024). "EGFR mutations activate signaling pathways associated with resistance to BRAF inhibitors and melanoma progression." (PMID 38534309, 2024). "MEK inhibitors such as trametinib, cobimetinib, binimetinib, and selumetinib have demonstrated promising outcomes in treating melanomas containing BRAF mutations." (PMID 38534742, 2024). "Vemurafenib was first designed for melanoma, and it has also been used to treat thyroid carcinoma with BRAF mutations." (PMID 38501105, 2024). "BRAF mutations are found in around 50% of all melanomas, with p.V600E being the most common mutation, accounting for 80–90% of BRAF-mutated melanomas." (PMID 38247727, 2024). "Just like EGFR mutations in specific lung cancers, or BRAF mutations in melanoma and certain thyroid cancers, several novel prognostic biomarkers for HNSCC have been identified through recent advancements." (PMID 39199313, 2024). "An additional factor in BRAF mutation melanoma survival is the level of autophagy present in melanoma samples." (PMID 38732242, 2024). "Currently, dabrafenib is approved for mutated BRAF V600E melanomas, non-small cell lung cancers, solid tumors that are unresectable or metastatic, and thyroid cancers." (PMID 39664200, 2024). "As already reported, melanoma patients harboring pTERT mutations in combination with BRAF/NRAS mutations have a significantly shorter PFS than patients without this combination." (PMID 38548846, 2024). "This discovery led to the development of BRAF inhibitors, such as vemurafenib and dabrafenib, which have significantly improved outcomes for patients with melanoma positive for BRAF mutations." (PMID 39518150, 2024). "Since the discovery of BRAF as a major driver mutation in melanoma, inhibitors of BRAF (BRAFis) have been developed and applied effectively in clinic settings." (PMID 39001376, 2024). "Significant differences were observed in the genomic landscape across three common cancer types with a high proportion of BRAF mutations: melanoma, NSCLC, and CRC." (PMID 38275886, 2024). "Recently, a pioneering study in a melanoma mouse model showed that BRAF-mutated tumors are resistant to BRAF inhibitors, mainly due to the aberrant activation of cancer-associated fibroblasts (CAFs)." (PMID 38448544, 2024). "The main finding is that the two main oncogenic drivers in melanoma, BRAF V600 and NRAS Q61 hotspot mutations, result in different underlying signaling biologies requiring different treatment regimes using the same drugs." (PMID 39199684, 2024). "BRAF mutations, particularly the V600E variant, occur in 66% of melanomas and less frequently in other cancers (OMIM:164757)." (PMID 39635441, 2024).